ASMT (acetylserotonin O-methyltransferase)
Description:
[Isoform 1]: Catalyzes the transfer of a methyl group onto N-acetylserotonin, producing melatonin (N-acetyl-5-methoxytryptamine). [Isoform 2]: Does not show Acetylserotonin O-methyltransferase activity. [Isoform 3]: Does not show Acetylserotonin O-methyltransferase activity.
Synonyms: HIOMT; ASMTY; HIOMTY
Tractability: Small molecule: a structure with a bound ligand is known.
Gene: Protein-coding gene on chromosome X (1,615,059 to 1,643,081, forward strand). Ensembl gene ENSG00000196433.
Pathways (Reactome):
Metabolism: Serotonin and melatonin biosynthesis
Gene Ontology:
Molecular function: acetylserotonin O-methyltransferase activity; identical protein binding; protein homodimerization activity; O-methyltransferase activity; S-methyltransferase activity; methyltransferase activity; protein dimerization activity
Biological process: melatonin biosynthetic process; indolalkylamine biosynthetic process; methylation; translation
Cellular component: cytosol
Homologues: Orthologues: chimpanzee ASMT (98% identical), macaque ASMT (84% identical), pig ASMT (67% identical), dog ASMT (66% identical), mouse Asmt (47% identical), rat Asmt (47% identical), zebrafish asmt (46% identical), tropical clawed frog asmt (46% identical). Paralogues in human: ASMTL (40% identical).
Diseases named in the same sentence as ASMT in open-access papers:
ASMT is named in the same sentence as 21 diseases in open-access papers, as found by Europe PMC text mining. Sharing a sentence is not in itself a finding about the gene and the disease. The quoted sentences say what the papers report.
autism (17 papers, 2010 to 2025). Persistent deficits in social interaction and communication and interaction as well as a markedly restricted repertoire of activity and interest as well as repetitive patterns of behavior. "Several likely gene-disruptive (LGD) variants in genes such as GRIK2 and ASMT affecting autism-risk were found exclusively or more frequently in individuals with autism compared to control groups." (PMID 40373085, 2025). "Several likely gene-disruptive (LGD) variants in genes such as GRIK2 and ASMT affecting autism risk were found exclusively or more frequently in individuals with autism than in control groups." (PMID 37790478, 2023). "Depressed levels of circulating melatonin have been associated with autism spectrum disorder, and clinical studies have classified ASMT as a susceptibility gene due to the highly significant association between ASMT activity and autism." (PMID 36519529, 2022). "Most of the variants identified in this study were found in autosomal genes, whereas one was identified in the X‐Y pseudoautosomal gene, ASMT, which has been reported to be associated with the autism phenotype and sleep disturbance." (PMID 31595719, 2019). "In summary, we performed a case-control study to explore the association between ASMT genetic variants and autism." (PMID 23349736, 2013). "To investigate the association between ASMT and autism, we sequenced all ASMT exons and its neighboring region in 398 Chinese Han individuals with autism and 437 healthy controls." (PMID 23349736, 2013). "Here we initially show that 39,XY*O mice are also deficient for the recently-characterised murine orthologue of the Xp22.3 autism candidate gene ASMT (encoding acetylserotonin-O-methyltransferase)." (PMID 23276394, 2013). "Line 2: ASMT deficiency is a molecular marker of autism,according to Melke and co-workers (2008), while a recent surveyof teenagers above 12 years of age with autism spectrumdisorders and epilepsy in past medical history revealed theirinclination to aggression." (PMID 38213701, 2023). "Further work identifying the mechanisms of circadian regulation of ASMT enzyme activity might inform us on the melatonin deficiency in autism." (PMID 33368564, 2021). "A large number of mutations of human ASMT gene have been screened to determine candidate alleles with some mental diseases, such as intellectual disability, attention‐deficit/hyperactivity disorder, bipolar disorder, autism." (PMID 32529744, 2020). "ASMT encodes the last enzyme in the melatonin biosynthesis pathway, low melatonin expression is observed in autism spectrum disorders, and rare ASMT mutations are associated with autism." (PMID 24988487, 2014). "Furthermore, the the genes in the melatonin metabolism pathways—such as Acetylserotonin O-Methyltransferase (ASMT) gene that encode the last enzyme of melatonin synthesis—may contribute to sleep problems in individuals on the autism spectrum." (PMID 35873241, 2022). "The Simons Foundation Autism Research Initiative (SFARI) [geneSFARI.org] lists four genes of Y chromosome associated with autism vizNLGN4Y, ASMT, USP9Y,andSHOX." (PMID 35169779, 2022). "Genetically, autism-associated mutations have been found in genes encoding the key enzymes of melatonin synthesis, Aralkylamine N-acetyltransferase (AANAT), and Acetylserotonin O-methyltransferase (ASMT), as well as a reduced expression of the gene encoding AANAT in ASD." (PMID 30804889, 2019). "In the same study, several mutations in the ASMT gene were identified, including a splice site mutation, IVS5+2T>C, that were associated with low ASMT activity and melatonin secretion, suggesting that the low ASMT activity in autism is, at least partly, due to variation within the ASMT gene." (PMID 20377855, 2010).
autism (continued). "Moreover, mutations in the ASMT gene have been identified, including a splice site mutation, that were associated with low ASMT activity and melatonin secretion, suggesting that the low ASMT activity observed in autism is, at least partly, due to variation within the ASMT gene." (PMID 20377855, 2010). "The 39,XY*O mouse, which lacks the orthologues of the ADHD and autism candidate genes STS (steroid sulphatase) and ASMT (acetylserotonin O-methyltransferase), exhibits behavioural phenotypes relevant to developmental disorders." (PMID 24602487, 2014). "Indeed, one consistent biological finding in autism is low levels of melatonin, and in a recent study, it could be demonstrated that this decrease of melatonin seems to be due to low activity of the acetylserotonin O-methyltransferase (ASMT), the last enzyme in the melatonin synthesis." (PMID 20377855, 2010).
autism spectrum disorder (6 papers, 2010 to 2022). A spectrum of developmental disorders that includes autism, and Asperger syndrome. "ASMT contains polymorphism in the promoter region which affects ASMT expression and was reported to be a risk factor of autism spectrum disorders." (PMID 34858185, 2021). "Mutations in ASMT gene, coding the last enzyme of the melatonin pathway have been reported as a risk factor for autism spectrum disorders (ASD), which are often comorbid with ID." (PMID 21251267, 2011). "Another possibility, perhaps implied by increased serotonin associated with autism spectrum disorder and presumably with the rs4446909 G allele, is that a crucial effect of reduced ASMT expression is accumulation of N-acetylserotonin, which we now appreciate may influence the BDNF-TRKB interaction." (PMID 21827647, 2011). "Taken together, previous data suggest that the ASMT gene and the melatonin signaling pathway may play an important role in the etiology of autism spectrum disorders." (PMID 20377855, 2010).
sleep disorder (4 papers, 2008 to 2025). A change from the patient's baseline sleeping pattern, in the hours slept and/or an alteration/dysfunction in the stages of sleep. "Further studies will be required to establish the precise link between ASMT variants, melatonin levels and sleep disorders." (PMID 21251267, 2011). "The ASMT gene encodes for the final enzyme required for melatonin biosynthesis, which suggests that these findings may partially explain the association between ASD and sleep disorders." (PMID 34627165, 2021). "Further studies on genetic variation in the ASMT gene, the effects of the CNV on gene expression, and the relationship of this CNV to both ASDs and sleep disorders are warranted." (PMID 18925931, 2008).
bipolar disorder (3 papers, 2013 to 2020). A disorder of the brain that causes unusual shifts in mood, energy, activity levels and the ability to carry out day-to-day tasks. "A polymorphism (rs4446909) of the promoter of the ASMT gene associated with bipolar disorder influences sleep and circadian rhythms, and it associated with lower ASMT transcription level and weaker activity in lymphoblastoid cell lines." (PMID 32529744, 2020). "Although ASMT is found in the autosomal portion of the X and Y chromosomes, ASMT likewise has been little examined in GWAS studies despite expanding evidence associating ASMT with unipolar depression and bipolar disorder." (PMID 23521777, 2013). "The Acetylserotonin O-Methyltransferase (ASMT) gene located in PAR, which is involved in circadian rhythm abnormalities, is considered as a candidate gene for bipolar depression." (PMID 30297990, 2018).
breast carcinoma (3 papers, 2020 to 2025). "In summary, the current study clearly illustrates that ASMT regulates the circadian clock system in breast cancer and that ASMT and clock proteins are overexpressed in breast cancer patients." (PMID 33194597, 2020). "Taken together, these results showed that breast cancer cell lines are good models to investigate the regulation between ASMT and the circadian clock system." (PMID 33194597, 2020). "The inhibition of ASMT reduced circadian clock protein levels in both breast cancer cell lines." (PMID 33194597, 2020). "Our study suggests that ASMT regulates the circadian clock system in breast cancer and inhibition of ASMT reduces the invasiveness of triple-negative breast cancer cells by downregulating clock protein in a certain extent, indicating the potential value of ASMT as a drug target for TNBC treatment." (PMID 33194597, 2020). "In addition, previous studies have found that ASMT can regulate the invasiveness of breast cancer cells, and may be a potential drug target in breast cancer." (PMID 36407768, 2022). "Cancer cells and primary breast cancer tissues were immunostained for the measurement of circadian clock proteins (CLOCK, BMAL1 and PER1) and acetylserotonin methyltransferase (ASMT)." (PMID 33194597, 2020).
depression (3 papers, 2011 to 2023). "Both MAOA and ASMT may influence melatonin metabolism, with polymorphisms possibly leading to delayed melatonin offset, triggering photoperiodic mechanisms which manifest as depression." (PMID 23521777, 2013).
epilepsy (2 papers, 2023). A brain disorder characterized by episodes of abnormally increased neuronal discharge resulting in transient episodes of sensory or motor neurological dysfunction, or psychic dysfunction. "Genetic variation in ASMT and another enzyme in the melatonin pathway, cytochrome P450 1A2 (CYP1A2), were identified in children with ASD and epilepsy and comorbid sleep onset delay." (PMID 37998056, 2023).
glioma (2 papers, 2022 to 2026). A benign or malignant brain and spinal cord tumor that arises from glial cells (astrocytes, oligodendrocytes, ependymal cells). "Then, four genes (IL4I1, CYP1A1, OGDHL, and ASMT) were screened out by univariate and multivariate cox regression analysis of tryptophan metabolism genes, and a risk score model for predicting the overall survival (OS) of glioma patients was constructed." (PMID 36407768, 2022). "The construction of our predictive model was based on the expression levels of four genes (IL4I1, CYP1A1, OGDHL, and ASMT) in glioma tissues." (PMID 36407768, 2022). "Combined with the results of our univariate Cox analysis, we can conclude that IL4I1 plays a tumor-promoting role and CYP1A1, OGDHL, and ASMT all play protective roles in gliomas." (PMID 36407768, 2022). "Among them, the expression of IL4I1 in glioma patients was greater than of normal samples, while the CYP1A1, OGDHL, and ASMT were lower in glioma samples." (PMID 36407768, 2022). "At the same time, we verified the expression of IL4I1, CYP1A1, OGDHL, and ASMT four genes in glioma specimens and cell lines in GES4260 and GES15824." (PMID 36407768, 2022). "Immunohistochemistry confirmed reduced MTNR1A and ASMT protein expression in glioma tissues." (PMID 42286740, 2026). "In this study, transcriptomic data from TCGA, CGGA, and GTEx were integrated to characterize the expression patterns of melatonin receptors (MTNR1A and MTNR1B) and biosynthetic enzymes (AANAT and ASMT) across normal brain tissue, lower-grade glioma and glioblastoma." (PMID 42286740, 2026). "We found that IL4I1 was highly expressed in glioma cell lines (LN018, LN215, LN229, and LN319), CYP1A1 was low expressed in glioma cell lines (LN215, LN229, LN319, and BS149), OGDHL was low expressed in LN018, and ASMT was lowly expressed in glioma cell lines (LN018, LN215, LN229, LN319, and BS149)." (PMID 36407768, 2022).
schizophrenia (2 papers, 2013 to 2019). A major psychotic disorder characterized by abnormalities in the perception or expression of reality. "Furthermore, recent studies detected that mutations in ASMT were associated with patients with attention-deficit/hyperactivity disorder (ADHD), and schizophrenia." (PMID 23349736, 2013).
myopia (1 paper, 2024). "The circadian clock gene PER3 and ASMT (whose protein product catalyzes the final step in melatonin synthesis) relate directly to potential circadian dysregulation in myopia, the hypothesis underlying this study." (PMID 39028695, 2024).
pineal parenchymal tumors (1 paper, 2013). "High Expression of ASMT gene is evident in pineal parenchymal tumors (PPTs)." (PMID 24156411, 2013). "The presence of abnormally high levels of ASMT in pineal gland could serve as an indication of the existence of pineal parenchymal tumors (PPTs) in the brain (J Neuropathol Exp Neurol 65: 675–684, 2006)." (PMID 24156411, 2013).
triple-negative breast carcinoma (1 paper, 2020). An invasive breast carcinoma which is negative for expression of estrogen receptor (ER), progesterone receptor (PR), and human epidermal growth factor receptor 2 (HER2). "Our data showed that knockdown of ASMT in triple-negative breast cancer cells significantly reduced cell migration and invasion, but this phenotype was reversed when CLOCK was over-expressed simultaneously." (PMID 33194597, 2020). "Nevertheless, the results demonstrate that inhibition of ASMT reduce the invasiveness of triple-negative breast cancer cells by downregulating clock protein in a certain extent." (PMID 33194597, 2020).
tumor (5 papers, 2016 to 2026). "Although the underlying mechanism involving ASMT, CLOCK, and tumor invasion still remains to be elucidated, we demonstrate that inhibition of ASMT leads to reductions in the invasiveness of TNBC cells by downregulating clock expression in a certain extent." (PMID 33194597, 2020). "Expression of AANAT, ASMT, MTNR1A and MTNR1B progressively declined with increasing tumour grade and was associated with poor prognosis." (PMID 42286740, 2026). "We observed a decrease in the expression of ASMT in OC, corroborating the present findings where tumor tissue had a lower concentration of melatonin." (PMID 35889222, 2022). "Our results indicate that ASMT may regulate tumor invasion through circadian clock system in TNBC patients." (PMID 33194597, 2020). "Being that several PAR genes are implicated to function as tumor suppressors, such as PPP2R3B, SHOX, SLC25A6, ASMT, and DHRSX, they serve as prime candidates for further investigation and may hold the greatest therapeutic promise." (PMID 27655702, 2016). "Further analysis showed that the expression levels of ASMT and circadian clock proteins did not correlate with clinical parameters such as age, tumor size, histologic grade and CK5/6, but increased significantly with lymphatic invasion in TNBC." (PMID 33194597, 2020).
cancer (2 papers, 2020 to 2021). A tumor composed of atypical neoplastic, often pleomorphic cells that invade other tissues. "In the present study, we showed that ASMT regulates the circadian clock system, which may reveal a new mechanism for cancer cell invasion and migration in TNBC." (PMID 33194597, 2020). "The downregulation of ASMT in TNBC may reduce cancer cell migration and invasion by inhibiting clock expression, providing a new molecular mechanism that regulates the invasiveness of TNBC." (PMID 33194597, 2020). "Among them, six melatonergic genes were significant unfavorable factors in cancers (e.g., MTNR1A in ESCA and LIHC; GPR50 in KIRC, LIHC, and STAD; NQO2 in BRCA, LIHC, and LUSC; CYP1B1 in KIRC and STAD; ASMT in ESCA, HNSC, and LUAD; and MTNR1B in STAD)." (PMID 33842355, 2021).
neurodevelopmental disorder (2 papers, 2014 to 2025). A behavioral and cognitive disorder with onset during the developmental period that involves impaired or aberrant development of intellectual, motor, or social functions. "Furthermore, in animal model studies with 39, XY*O mice, which have an Xp22.3 deletion and a relevant neurodevelopmental disorder phenotype, ASMT enzyme deficiency was also found to be associated with hyperactive symptoms, inflammatory responses, and altered synapses." (PMID 39997758, 2025). "We anticipated that these combined approaches might reveal new pathophysiological mechanisms underlying phenotypes associated with STS/ASMT deficiency specifically and neurodevelopmental disorders more generally, and might highlight novel factors protecting against behavioural disinhibition." (PMID 24602487, 2014).
ASMT also shares sentences with these, for which no sentence is quoted: Intellectual disability (2 papers); lymphocytic colitis (2); brucellosis (1); glioblastoma (1); infectious disease (1); viral infections (1).